ERBB2 (erb-b2 receptor tyrosine kinase 2)
Diseases named in the same sentence as ERBB2 in open-access papers (continued):
Sharing a sentence is not in itself a finding about the gene and the disease.
cancer (continued). "ErbB2/HER2 (human epidermal growth factor receptor 2) is one of the important protein targets for cancer treatment." (PMID 30276148, 2018). "The highest frequency genes in CNGs, BIRC5, ERBB2 and EZH2 were used to perform a pan-cancer mutational analysis." (PMID 29459674, 2018). "Together, these critical data demonstrate that ErbB2+ cancer cells are preferentially sensitive to the anti-cancer effects of ganetespib, particularly on cell proliferation, which indicate the fundamental role of ErbB2 in the targeted effects of ganetespib." (PMID 29717218, 2018). "Hundreds of FOXP3 target genes have been identified in both Treg cells and cancer cells so far, including HER2/ERBB2, SKP2, CD44, BRCA1, p21, and LATS2." (PMID 30011797, 2018). "We have reported that apoptosis was rapidly activated in mammary cells following ErbB2 activation to provide a barrier to cancer." (PMID 29778097, 2018). "For example, many growth factor receptors such as EGFR, VEGFR, ERBB2, which are amplified in cancers, can also generate a soluble decoy receptor by alternative splicing." (PMID 30329087, 2018). "In particular, HSP90 inhibitors in combination with ErbB2-targeting therapeutics have shown promising anti-cancer efficacy." (PMID 29717218, 2018). "Specifically, MYC, CDK6, PRKACA, and ERBB2, all well-known oncogenes and cancer markers, were overexpressed in conjunction with LYL1 gene amplification." (PMID 29716549, 2018). "Collectively, these findings conclude that miR-3622b-5p is a regulator of ERBB2 in ERBB2-positive cancers." (PMID 28160563, 2017). "We also noticed that an increase of the density of cancer cells detached from the ECM downregulates a Mek effector protein kinase Erk and causes ErbB2 loss." (PMID 29285258, 2017). "In their study, alcohol increased cancer stem cell populations with colocalized activation of ErbB2, and promoted colon and lung metastases." (PMID 28369097, 2017). "Trastuzumab resistance is a common problem that impedes the effectiveness of trastuzumab in ErbB2-amplified cancers." (PMID 28514745, 2017). "Taken together, miR-3622b-5p is involved in the proliferation and apoptosis of human ERBB2-positive cancer cells via targeting ERBB2/mTORC1 signaling pathway." (PMID 28160563, 2017). "After studying the on-chip and chip-to-chip variability of the detection antibody binding step (that was in the low percent range), we focused our attention on the optimization of a cancer biomarker assay for ERBB2 positive and control lysates." (PMID 28817097, 2017). "ERBB2 point mutations and CNVs were only detected in HER2+ cancers, and the mutant frequency in the HER2+ group was 8.8%." (PMID 28729728, 2017). "We report on the use of one-dimensional photonic crystals to detect clinically relevant concentrations of the cancer biomarker ERBB2 in cell lysates." (PMID 28817097, 2017). "ErbB2-targeted therapy is a successful example as personalized cancer treatment that has made a significant progress in clinical outcomes." (PMID 28881779, 2017). "To put into context, ERBB2 expression levels in cancer cell lines overexpressing ERBB2 and iPSC-derived cardiomyocytes, we examined RNA and protein expression levels of the ERBB family." (PMID 28101782, 2017). "Human epithelial growth factor receptor 2 (HER2/ErbB2) is a ligand-less tyrosine kinase receptor that acts as a pro-oncogene in different human cancers." (PMID 28841157, 2017). "In conclusion, miR-3622b-5p is involved in the proliferation and apoptosis of ERBB2-positive cancer cells via targeting ERBB2/mTORC1 signaling pathway." (PMID 28160563, 2017). "Following Bonferroni correction of each GO term, a total of 272 GO terms were associated at p < 0.05 with differentially expressed genes in ERBB2-overexpressing cancer cell lines treated with trastuzumab." (PMID 28101782, 2017).
cancer (continued). "Both curcumin and EGCG were shown to decrease ErbB2 expression and phosphorylation as well as downstream signaling molecules involved in survival and proliferation of the cancer cells." (PMID 28286519, 2017). "The results showed that miR-3622b-5p was significantly down-regulated in human ERBB2-positive cancer tissues, compared with that in ERBB2-negative cancer tissues." (PMID 28160563, 2017). "Of these, 22 genes were classified as transcription factors in MSigDB and 15 genes were found in the COSMIC Cancer Gene Census, including ERBB2 (Colo678), MYC (SW480), PPFIBP1 (IS1), and RAD21 (HT29)." (PMID 28683746, 2017). "MiRNA subtypes, including miR-548d-3p, miR-559, miR-125a, miR-125b, miR-205, miR-155 and miR-4728, target ERBB2 and are downregulated in cancers." (PMID 28160563, 2017). "Due to its enhanced expression in cancers and involvement in essential signaling processes, ErbB2 constitutes an important target for cancer therapy." (PMID 29050225, 2017). "Gene expression of all members of the ERBB family of tyrosine kinase receptors was detected in cardiomyocytes and cancer cell lines overexpressing ERBB2." (PMID 28101782, 2017). "In this experiment, miR-3622b-5p was down-regulated in ERBB2-positive cancer tissues, suggesting its suppressive role in ERBB2-positive cancer." (PMID 28160563, 2017). "Cellular signaling was represented by pathways that drive proliferation in ER+ and ERBB2+ cancer cells (e.g., MAPK, EGFR/ERBB2 and estrogen signaling), and additional downstream pathways involved in proliferation, apoptosis and survival." (PMID 29269772, 2017). "This is of interest because aside from gatekeeper mutations, there is also evidence that FGFR inhibitor resistance can come from a switch to ERBB2/3 signaling (structurally related to EGFR) in models of FGFR3-dependent cancer cell lines." (PMID 28030802, 2017). "Human epidermal growth factor receptor 2 (HER2 or ErbB2) can be overexpressed, amplified and/or mutated in malignant tumors, and is a candidate for therapeutic targeting." (PMID 28146588, 2017). "The identification of cancer sub-type relies on the expression of the estrogen receptor (ER), progesterone receptor (PR), epidermal growth factor receptor 2 (ERBB2), and cytokeratin (CK) protein." (PMID 29657291, 2017). "Given the increasing efforts to find pharmacologically safe natural compounds with anticancer properties, our results warrant further in vivo studies to establish the full potential of CA or CA analogues as adjuvant drugs in the treatment of ERBB2+ cancers." (PMID 29100552, 2017). "MiR-3622b-5p turned ERBB2-positive cancer cells more vulnerable to the apoptosis induced by cisplatin and 5-fluorouracil." (PMID 28160563, 2017). "Here the authors show that p140Cap interferes with ERBB2-dependent activation of Rac GTPase-controlled circuitries reducing metastasis and cancer progression." (PMID 28300085, 2017). "This analysis showed the presence of the protein p27KIP1 in the nuclei of CA + Tz ERBB2+ treated cancer cells." (PMID 29100552, 2017). "TOLE can inhibit cell growth in cancer cells through cyclooxygenase-independent pathways including inhibition of ErbB2 expression, activation or ATF3, or induction of NSAID-activated gene-1 (NAG-1) and EGR1." (PMID 29228577, 2017). "In particular, we treated these cells for 7d with the maximal concentration of CA and Tz used for the ERBB2+ cancer cell lines (37.5 μM CA and 10 μg/ml Tz, respectively) and performed the MTT assay." (PMID 29100552, 2017). "In this study, miR-3622b-5p made ERBB2-positive cancer cells more vulnerable to the apoptosis induced by cisplatin and 5-FU." (PMID 28160563, 2017). "Overexpression of the ERBB2 protein and its receptor on the surface of cancer cells are highly correlated to MBC occurrence." (PMID 28885562, 2017). "We have developed an in vitro system of cancer cell redirection that employs the 1:50 ratio of erbB2-overexpressing cancer cells to normal cells." (PMID 28594912, 2017).
cancer (continued). "Over-expressed miR-3622b-5p reduced the protein level of ERBB2, weakened the activation of mTORC1/S6, and induced the apoptosis of ERBB2-positive cancer cells." (PMID 28160563, 2017). "The resolution obtained in both modes meets international guidelines and recommendations (15 ng/mL) for ERBB2 quantification assays, providing an alternative tool to phenotype and diagnose molecular cancer subtypes." (PMID 28817097, 2017). "This is in contrast to ERBB2-overexpressing cancer cell lines treated with trastuzumab, in which the most significantly enriched categories related to cell cycle." (PMID 28101782, 2017). "ErbB2-positive cancer cells largely depend on EGFR/ErbB2 signaling for their glucose uptake which was recently reported as a major factor in oncogenic KRAS pathway mutations." (PMID 28288164, 2017). "As expected, ERBB2 expression was significantly higher in the ERBB2-overexpressing cancer cell lines (mean 12.9 log2 counts per million), but ERBB2 was also expressed in iPSC-derived cardiomyocytes, 8.96 log2 counts per million." (PMID 28101782, 2017). "The amplification of ERBB2 gene produces an overexpression of HER2 protein that leads to cancer cells survival, growth, and proliferation through the PI3K-AKT and the MAPK pathways." (PMID 29094049, 2017). "The roles of EGFR and ErbB2 in cancer development are presently well established, whereas data on ErbB3 and ErbB4 are still rather fragmentary." (PMID 28417948, 2017). "We observed a high degree of overlap in the genes expressed in iPSC-derived cardiomyocytes and ERBB2-overexpressing cancer cell lines." (PMID 28101782, 2017). "In cancer cells, the extracellular fragment of E-cadherin can also bind to ErbB2 to promote cell migration." (PMID 28829038, 2017). "The resistance to ErbB antibodies may be caused by nuclear localization of ErbB2, miRNA production, higher Akt signaling, or steric hindrance by other membrane proteins and raises the need for other therapeutic compounds useful in the treatment of ErbB overexpressing cancers." (PMID 28286519, 2017). "Reduced erbB2 phosphorylation is one mechanism involved in cancer cell redirection and detection of reduced receptor activity serves as a biomarker of cancer cell redirection." (PMID 28594912, 2017). "TCGA data analysis of various cancer types showed that genes co-amplified with MET or ERBB2 had high amplification frequencies in other cancers." (PMID 29190909, 2017). "The results showed that genes co-amplified with MET or ERBB2 also show high amplification frequency in cancers other than GC." (PMID 29190909, 2017). "There are several clinically available EGFR or Erbb2 inhibiting cancer therapies, with low or minimal known cardiotoxicity." (PMID 28924210, 2017). "Particularly the activation of EGFR / ErbB1 and ErbB2 has been shown to be important in the progression of different human cancers, and decorin has been shown to interact with both of them." (PMID 28653173, 2017). "As further validation of changes in gene expression mediated by ERBB2 inhibition, we next assessed the overlap of trastuzumab induced differential gene expression between the ERBB2-overexpressing cancer cell lines and iPSC-derived cardiomyocytes." (PMID 28101782, 2017). "ERBB2 induction of migration and invasiveness of cancer cells require the activation of small GTPases and mTORC1 signaling." (PMID 28160563, 2017). "Patient #2 possessed a germline heterozygous BRCA2 E49* mutation that underwent loss of heterozygosity in the patient’s cancer, a possibly oncogenic FLT4 E766D somatic mutation, and moderate ERBB2 amplification (5 copies) at all timepoints." (PMID 29093439, 2017). "Increasing the expression levels of EGFR family proteins, including EGFR, ErbB2, ErbB3, and ErbB4, can promote the growth of cancer cells." (PMID 29164150, 2017).
cancer (continued). "The recently developed multi-kinase inhibitor SKLB1206 showed promising results in inhibiting not only EGFR with gefitinib-sensitive and -resistant mutations but also showed considerable inhibition potency against ErbB2 and ErbB4 in cancer cell lines." (PMID 28417948, 2017). "We note at this point, a similar pattern in trastuzumab-induced down-regulation of ERBB2 protein levels between cancer cells and cardiomyocytes." (PMID 28101782, 2017). "ErbB2, a member of the ErbB family of receptor tyrosine kinases, triggers numerous oncogenic signals in cancer cells by binding other members of the family, such as Epidermal Growth Factor Receptor (EGFR) or ErbB3." (PMID 29285258, 2017). "Second, major oncoproteins, e.g. ErbB2, Ras and β-catenin, promote anchorage-independent survival and growth of cancer cells." (PMID 29285258, 2017). "Collectively, these results suggest that miR-3622b-5p inhibits the proliferation and induces the apoptosis of ERBB2-positive cancer cells." (PMID 28160563, 2017). "Aberrant activation of ERBB2 and PI3K-AKT pathway is associated with tumorigenesis, carcinoma progression and drug resistance." (PMID 29163776, 2017). "Collectively, our data show that hPEPD-G278D is a strong dual inhibitor of ErbB1 and ErbB2 in cancer." (PMID 27286447, 2016). "ERBB2 (HER2) is expressed in solid carcinomas including cancers of the breast, stomach, lung and pancreas." (PMID 27825109, 2016). "Herein, we examined crosstalk between ErbB2 and IRSs using cancer cell lines and transgenic mouse models." (PMID 27765041, 2016). "Another molecule quercetin, a flavonoid present in fruits and vegetables, is a chemopreventive agent in cancer; shows its beneficiary effects by down regulating ErbB2 and upregulating its E3 ubiquitin ligase CHIP." (PMID 27757073, 2016). "A similar mechanism of action has been observed for antibodies approved by FDA for cancer treatment, e.g. Trastuzumab (targets ERBB2), Cetuximab (targets EGFR), Rituximab (targets CD20) and Bexxar (targets CD20)." (PMID 27270318, 2016). "Most studies have focused on pathways modulating cancer cell sensitivity, such as the transmembrane ATP-dependent efflux pump P-glycoprotein (P-gp), Her-2/ERBB2, the Bcl-2 family proteins, and, more recently, miRNAs." (PMID 27566564, 2016). "The ErbB2 gene is amplified in diverse types of cancer, and as a result it is a target for an effective cancer therapy using a humanized antibody, Herceptin." (PMID 27175488, 2016). "Many lines of evidence indicate that targeting ErbB1 and ErbB2 is an important cancer therapeutic approach." (PMID 27286447, 2016). "ErbB2 and ErbB3 form a heterodimer and perform a central role in maintenance and malignancy of lung and other cancers, through activating the phosphatidylinositol-4,5-bisphosphate 3-kinase (PI3K) pathway." (PMID 27480244, 2016). "CCBs were even more strongly associated with more aggressive tumors, (OR for invasive tumors = 1.96, 95% CI = 1.09 to 3.53; OR for non ductal cancers = 3.97, 95% CI = 1.73 to 9.05; OR for Erbb2+ cancer = 2.97, 95% CI: 1.20 to 7.32)." (PMID 27508297, 2016). "Human epidermal growth factor receptor Her2, also known as Neu, ErbB-2, or p185, has emerged as an important target for cancer immunotherapy." (PMID 27471642, 2016). "Despite this general theme, the principles of ErbB2 signaling in physiological conditions, including the regulation of cardiac function, are fundamentally different from those in cancer cells." (PMID 27596216, 2016). "During the past decade, we have witnessed the introduction of several new drugs to target ErbB2 in cancer." (PMID 27596216, 2016). "A better understanding of septin contribution to the abnormal persistence of EGFR and ErbB2 in cancer cells will provide a potential treatment target for aggressive malignancies." (PMID 28066764, 2016). "In conclusion, we show that ERBB2 exploits the trafficking function of TOM1L1 to promote cancer cell invasion." (PMID 26899482, 2016).
cancer (continued). "Accordingly, nucleolin inhibition reduces cell viability and ErbB2 activation in ErbB2-positive cancer cells." (PMID 27542246, 2016). "HER2-enriched cancers show amplification and high expression of the ERBB2 gene and several other genes of the ERBB2 amplicon." (PMID 27058625, 2016). "Many tyrosine kinase inhibitors and monoclonal antibodies against EGFR and ERBB2 RTK have successfully been used as cancer drugs, for example cetuximab and panitumumab for EGFR overexpression, and afatinib and dacomitinib as pan-HER inhibitors." (PMID 26907936, 2016). "Many studies have further shown that even when cancers progress after trastuzumab therapy, ErbB2 still remains a valid therapeutic target, suggesting that ErbB2 still represents a major vulnerability for ErbB2-positive cancer cells." (PMID 27564098, 2016). "The new emerging anti-cancer strategies, involving downregulation of ErbB2, also focus on the CHIP-mediated degradation of this protein in association with molecular chaperones." (PMID 27757073, 2016). "Many lines of evidence indicate that targeting both ErbB1 and ErbB2 is an important approach in cancer treatment." (PMID 27286447, 2016). "One molecular target with high potential for targeted cancer therapy is the human epidermal growth factor receptor 2 (HER2, also known as ErbB2)." (PMID 27213406, 2016). "Our results show that hPEPD-G278D effectively targets both ErbB1 and ErbB2 in ErbB1-overexpressing human cancer cells in vivo." (PMID 27286447, 2016). "ErbB2-nucleolin complexes are formed endogenously in both normal and cancer cells, and their effect on tumorigenicity is mediated through activation of ErbB2 signaling." (PMID 27542246, 2016). "Since ErbB2 is more prone to dimerization than other family members, when amplified it is frequently involved in cancer development." (PMID 27542246, 2016). "Given that hPEPD-G278D is a human protein and is unlikely to interfere with the enzymatic function of endogenous PEPD in normal cells, it is a highly promising agent for combating ErbB2-overexpressing cancer." (PMID 27286447, 2016). "We conclude that hPEPD-G278D is a dual inhibitor of ErbB1 and ErbB2 and selectively targets cancer cells overexpressing ErbB1 and/or ErbB2." (PMID 27286447, 2016). "In our study, expression of the SLC3A2-NRG1 fusion gene increased cancer cell proliferation in vitro and in vivo through ERBB2 and ERBB3 heterocomplexes." (PMID 27626312, 2016). "Even when cancers progress after multiple ErbB2-directed therapies, ErbB2 still remains a valid therapeutic target." (PMID 27564098, 2016). "The human epidermal growth factor receptor 2 (HER2/ErbB2) is overexpressed in a number of human cancers." (PMID 27469139, 2016). "Plasma extracted from 171 patients with a variety of cancers was analyzed for ctDNA (54 genes and copy number variants (CNVs) in three genes (EGFR, ERBB2 and MET))." (PMID 26848768, 2016). "Nevertheless, p-ErbB3 levels declined instantly in response to ErbB2 blockade by both agents, and in most ErbB2-depended cancer cells there was a permanent reduction of p-ErbB3." (PMID 27255951, 2016). "MAPKs are the intracellular effectors of ErbB receptors (EGFR, ErbB2, ErbB3 and ErbB4), and hyperactivation of the ERK1/2 MAPK signaling pathway frequently occurs in human cancer and is associated with increased cell survival and proliferation." (PMID 26843616, 2016). "Lapatinib is a clinically approved dual inhibitor of ErbB1 and ErbB2 in cancer, but its mechanism differs from that of hPEPD-G278D." (PMID 27286447, 2016). "Human epidermal growth receptor 2 (Her2, Neu, ErbB2) is a driver oncogene in human cancers, particularly breast cancers." (PMID 27527860, 2016).